CCDC171 (coiled-coil domain containing 171)
Synonyms: C9orf93; FLJ39267; FLJ46740; Em:AL513423.1; bA778P13.1; bA536D16.1
Tractability: PROTAC: ubiquitination databases record sites on it.
Gene: Protein-coding gene on chromosome 9 (15,552,899 to 16,061,663, forward strand). Ensembl gene ENSG00000164989.
Subcellular location (Human Protein Atlas): Nucleoplasm; Nucleoli
Genetic constraint (gnomAD): Loss-of-function variants: 102 observed, 96.21 expected, observed/expected ratio (o/e) 1.06, 90% interval 0.9 to 1.25. The synonymous counts are far from expectation, so gnomAD's model fits this gene poorly and the ratio says little. Missense variants: 1,358 observed, 1,072.6 expected, observed/expected ratio (o/e) 1.27, 90% interval 1.21 to 1.32. Synonymous variants: 471 observed, 393.02 expected, observed/expected ratio (o/e) 1.2, 90% interval 1.11 to 1.29.
Homologues: Orthologues: chimpanzee CCDC171 (99% identical), macaque CCDC171 (97% identical), rabbit CCDC171 (92% identical), pig CCDC171 (92% identical), dog CCDC171 (89% identical), guinea pig CCDC171 (89% identical), mouse Ccdc171 (87% identical), rat AABR07049060.1 (85% identical), tropical clawed frog ccdc171 (44% identical).
Diseases named in the same sentence as CCDC171 in open-access papers:
CCDC171 is named in the same sentence as 6 diseases in open-access papers, as found by Europe PMC text mining. Sharing a sentence is not in itself a finding about the gene and the disease. The quoted sentences say what the papers report.
Allergy (1 paper, 2017). An allergy is an immune response or reaction to substances that are usually not harmful. "However, nonsynonymous mutations were identified in the coding sequences of Cer1, Ttc39b, Ccdc171, Cntln, Adamtsl1, Haus6, Gm12551, and Dennd4c, but these genes do not have any prior documented associations with allergy, IgE, or asthma." (PMID 28696925, 2017).
CCDC171 also shares sentences with these, for which no sentence is quoted: asthma (1 paper); nervous system diseases (1); Obesity (1); ovarian carcinoma (1); serous ovarian cancer (1).